MIF (macrophage migration inhibitory factor)
Diseases named in the same sentence as MIF in open-access papers (continued):
Sharing a sentence is not in itself a finding about the gene and the disease.
unstable angina pectoris (1 paper, 2015). "The plasma MIF levels of stable angina pectoris (SAP) subgroup, unstable angina pectoris (UAP) subgroup, and control group were 61.52 ± 4.3 ug/L, 66.79 ± 6.29 ug/L, and 48.08 ± 6.48 ug/L, respectively." (PMID 25821795, 2015).
varicocele (1 paper, 2020). A condition characterized by the dilated tortuous veins of the spermatic cord with a marked left-sided predominance. "Nonetheless, proteins, such as CLGN, FTH1, MDH1, MIF, PPP3CA, SUCLA2, and PSMA7, involved in sperm function, apoptosis, and oxidative stress were present in a low and very low abundance in the unilateral and bilateral varicocele group, respectively." (PMID 32365753, 2020).
Vertigo (1 paper, 2019). An abnormal sensation of spinning while the body is actually stationary. "There was a significant decrement in MIF level 1 month after the vertigo attack compared with its values during the attack (P<0.001)." (PMID 31406010, 2019).
viral myocarditis (1 paper, 2025). Myocarditis that is caused by an infection with a viral agent. "Notably, serum MIF concentrations were significantly increased 7-14 days post-infection in a mouse model of viral myocarditis after CVB3 infection." (PMID 40092999, 2025). "Treatment of these mice with an anti-MIF antibody increased survival, decreased disease severity, and decreased IL-1β and TNF-α in the myocardium, suggesting MIF inhibition as a viable treatment option for dampening the inflammatory response in viral myocarditis." (PMID 40092999, 2025).
tumor (769 papers, 2005 to 2026). "Higher MIF levels were further associated with larger tumor dimension, while IL-8/CXCL8 was associated with increased bilirubin level and recent weight loss (p < 0.05)." (PMID 42122077, 2026). "Single-cell analysis showed SLC10A3 enrichment in tumor-associated astrocytes and macrophages, with enhanced astrocyte-macrophage crosstalk through MIF, MDK, and extracellular matrix remodeling pathways." (PMID 42211491, 2026). "Another study reported that, elevated levels of MIF were significantly associated with advanced tumor stage, increased lymph node invasion, and poor survival and prognosis, making it a possible prognostic biomarker." (PMID 41159021, 2025). "Implantation of YUMMER1.7 tumors into MIF-KO mice or mice with a low-expression human MIF allele (CATT5) showed that decreased host MIF was associated with decreased tumor growth." (PMID 41122966, 2025). "Of note, MIF increases Treg activities; thus, MIF increases the formation of tumor-associated Tregs that are crucial in maintaining immunological tolerance in the TME." (PMID 41159021, 2025). "Although several in vivo studies have implicated MIF in tumor initiation and progression, its role in sustaining established tumors, particularly when derived from epithelial tumor cells, remained unclear." (PMID 40835826, 2025). "Identified tumor associated proteins like MIF and cyclophilin A from tissue profiling showing useful biological targets from MALDI profiling." (PMID 41228317, 2025). "Others have shown similar delays in tumor growth with loss of host MIF expression, potentially due to alterations in macrophage populations and angiogenesis." (PMID 41122966, 2025). "To understand the mechanisms underlying anti–PD-1/anti-MIF–induced tumor regression, we first measured representative circulating cytokines and chemokines in plasma collected from YUMMER1.7 tumor–bearing mice prior to and after 2 doses of treatment." (PMID 41122966, 2025). "High levels of MIF can cause immunosuppressive phenotypes, which prevent efficient anti-tumor responses." (PMID 41159021, 2025). "The impact of MIF loss or inhibition on tumor cells is also likely cell‐line and context‐dependent, as other tumor models have shown mixed results related to MIF's role in proliferation and tumor growth." (PMID 40131169, 2025). "MIF acts on a wide array of immune cells, including macrophages, T cells, dendritic cells, Tumor-Associated Neutrophils (TANs), Myeloid-Derived Suppressor Cells (MDSCs), and natural killers’ cells." (PMID 41159021, 2025). "Among them, MIF plays a key role in regulating myeloid-derived suppressor cells (MDSCs) and tumor-associated macrophages (TAMs)." (PMID 40941008, 2025). "Eventually, loss of MIF drives M1-to-M2 transition at the tumor edge and leads to disease progression." (PMID 40058234, 2025). "MIF plays a significant role in tumor growth and progression by promoting tumor-associated angiogenesis." (PMID 41159021, 2025). "Within the tumor microenvironment, macrophages and B cells contribute to tumor-associated paracrine signaling through the MIF pathway." (PMID 41127012, 2025). "Mechanistically, MNAT1 coordinates with tumor-associated macrophages through the MIF and IFN-II signaling axis, synergistically driving OSCC progression via immune microenvironment remodeling." (PMID 41235252, 2025). "intercellular communication analysis indicates that high S1P epithelial cells can promote angiogenesis and influence the polarization of tumor-associated macrophages (TAMs) through the macrophage migration inhibitory factor (MIF) pathway." (PMID 40589755, 2025). "Lungs from MIF-deficient mice showed a noticeable reduction in metastatic tumor burden, both visually and in terms of total lung mass." (PMID 41159021, 2025). "Over the last two decades, MIF has been linked to carcinogenesis, invasion, metastasis, tumor-induced angiogenesis, and disease prognosis and diagnosis of several solid malignancies." (PMID 41159021, 2025).
tumor (continued). "Collectively, these studies demonstrate that the tumor or tumor‐associated fibroblasts are the main contributors of MIF expression, and that MIF pathologically shapes the immune landscape to contribute to an immune suppressive tumor microenvironment." (PMID 40131169, 2025). "In CRC, MIF is aberrantly elevated in tumor cells and is associated with poorer survival outcomes and reduced responses to therapy." (PMID 40835826, 2025). "Despite enhancing cytotoxic NKT cells, AG activates tumor‐associated mast cells (TAMCs) and inflammatory CAFs through MIF signaling." (PMID 41159485, 2025). "Inhibition of MIF or loss of Mif in tumor cells reverses the immunostimulatory effects of CDK4/6i on macrophages and subsequent CD8+ T cell antitumor immunity." (PMID 41082324, 2025). "Aberrant overexpression of MIF in CRC has been closely linked with tumor aggressiveness, invasiveness, metastasis, poor prognosis, and resistance to chemotherapy." (PMID 41294749, 2025). "Recently, MIF has been implicated in tumor immunity; it can establish both pro-inflammatory and immunosuppressive environments depending on the context." (PMID 41159021, 2025). "Upregulation of the MIF pathway has been shown to contribute to tumor growth and immune suppression and is associated with poor prognosis in HCC." (PMID 40315269, 2025). "These cells stimulated immunosuppression and tumor-associated macrophage (TAM) differentiation by interacting with macrophages via MIF-(CD74+CD44) signaling." (PMID 40936936, 2025). "In CAFs, PIAS1+ cells showed downregulation of immunosuppressives MIF–CD74_CD44 signaling and upregulation of tumor-suppressive CD99–CD99 interactions associated with immune activation." (PMID 40941002, 2025). "Macrophage migration inhibitory factor (MIF) signaling, which has been associated with decreased tumor survival and immune modulation, was identified as originating primarily from NB cells, with B lymphocytes acting as the main recipients in malignant tumors." (PMID 40190189, 2025). "CD74, known as an invariant chain of the MHC‐II complex and a receptor for MIF, is frequently associated with high expression and poor prognosis during tumour development." (PMID 40411322, 2025). "Macrophage migration inhibitory factor (MIF), a proinflammatory cytokine associated with tumor progression, has emerged as a promising biomarker in CRC." (PMID 41294749, 2025). "Early when the treatment is still effective, bevacizumab reduces tumor cell MIF expression (MIF promotes M1 polarization, causing macrophages to be less phagocytic) that increased proliferation of TAMs at the tumor edge." (PMID 40058234, 2025). "Although MIF expression alone does not significantly affect overall survival, CD163 expression—on tumor-associated macrophages—has been linked to disease-free survival, suggesting that MIF influences the TME in patients with triple-negative BC." (PMID 41159021, 2025). "The heatmap shows that malignant cells predominantly emit signals in the MIF signaling pathway, whereas B cells and tumor-associated macrophages primarily act as signaling recipients." (PMID 38927691, 2024). "Specifically, the role of miR451-mediated interactions between MIF and tumor-associated macrophages, including their potential to either promote or inhibit tumor growth, represents a significant area for forthcoming studies." (PMID 39076992, 2024). "MIF can activate myeloid-derived suppressor cells (MDSCs) and tumor-associated macrophages (TAM), which act together to inhibit T cells and thus leading to the generation of a microenvironment that promotes tumor growth." (PMID 38685050, 2024).
tumor (continued). "We underlined the value of CAFs in regulating tumor-promotion functions of myeloid cells through the production of MIF, CSF1, CXCL12, and FN1." (PMID 39323622, 2024). "Overexpression of MIF in various cancer types is associated with increased tumor aggressiveness and adverse prognostic outcomes." (PMID 38596689, 2024). "In vivo experiments have demonstrated that MIF plays a protective role against tumour initiation linked to inflammation." (PMID 39439893, 2024). "The Syrian hamster macrophage migration inhibitory factor (MIF) is structurally and functionally similar to humans and significantly enhanced tumor growth and promoted tumor-associated angiogenesis in Syrian hamster tumor models." (PMID 36923404, 2023). "The peptide C36L1, a 17-mer peptide that binds to CD74 on tumor-associated macrophages and DCs, was shown to block MIF’s immunosuppressive activities in melanoma models in vitro as well as in vivo." (PMID 36672343, 2023). "The epigenetic silencing of the miR-144/451a cluster induced by EZH2-catalyzed histone H3K27 methylation increases HGF and MIF expression promoting M2 polarization and the genesis of tumor-associated macrophages (TAMs)." (PMID 37958352, 2023). "We observed 3 tumor-associated macrophage (TAM) populations including a previously identified SPP1 + TAM that expressed MIF, which has been associated with alternative activation." (PMID 37633924, 2023). "Macrophage migration inhibitory factor (MIF) is now emerging as a prospective anti-angiogenic therapy in GBM as high levels of MIF have recently been linked to tumor recurrence and poor survival." (PMID 37218976, 2023). "The increase in EMT was also tested in vivo, whereby the administration of recombinant human MIF caused an increment in tumor size and in EMT." (PMID 36672343, 2023). "Further in-depth study of each signaling pathway verified that monocytes were directly associated with tumor cells only in the MIF and TNF pathways, in which the most important ligand-receptors were CD74/CD44 and TNF/TNFRSF1B." (PMID 36479092, 2022). "The MIF/CXCR4 axis has been described in different cancer types as a critical autocrine pathway linked to tumor progression." (PMID 35715791, 2022). "In an in vivo study, MIF-deficient mice showed markedly reduced neutrophils infiltration, tumor incidence and angiogenesis upon chronic UVB exposure." (PMID 35842634, 2022). "The high levels of CXCL8 and MIF are also suggestive of involvement of tumor-associated macrophages." (PMID 36230823, 2022). "In NB, MIF expression has been reported to be associated with tumor progression, immune evasion, inflammation, expression of pro-angiogenic factors, and MYCN oncogene." (PMID 35715791, 2022). "Downregulation of MIF in BC is associated with a significant increase in infiltration and anti-tumor functions of CD4+ and CD8+ T cells." (PMID 35842634, 2022). "In this review, we summarized the main effects and related mechanisms of tumor-associated MSCs (TA-MSCs), TA-MSCs-EVs, and MIF on tumors, and described their relationships." (PMID 35842634, 2022). "Tumour-associated macrophages secrete matrix metalloproteases (MMPs) in an MIF-dependent manner, which promotes proliferation of tumour cells and TME neovascularisation." (PMID 34944851, 2021). "In patients after partial tumor nephrectomy, circulating MIF concentrations were associated with the length of kidney ischemia during the surgery, suggesting that MIF was released during renal ischemia." (PMID 35096904, 2021). "MIF production is upregulated in hypoxic conditions associated with tumor development and progression." (PMID 33776775, 2021). "We observed a decreased growth in Mif-depleted organoids, further confirming, that MIF loss reduces tumor cell proliferation." (PMID 33542244, 2021).
tumor (continued). "CD74 is a cell surface receptor for macrophage migration inhibitory factor and is associated with tumour progression and metastasis." (PMID 34957096, 2021). "MIF/CD74 is a well-established pro-tumorigenic signalling in several solid malignancies partially by participating in the alternate activation of tumour‐associated macrophages." (PMID 34187256, 2021). "Multiple studies have documented that elevated MIF expression was associated with increased tumor aggressiveness, reduced sensitivity to gemcitabine, and worse survival in PDAC patients." (PMID 35002712, 2021). "The mechanism by which loss of tumor-derived MIF increased DC tumor accumulation was attributed to enhanced tumor cell cytolysis and ensuing tumor-associated antigen release." (PMID 33324425, 2020). "Although MIF is a proinflammatory cytokine, it also exerts immunosuppressive functions, influencing the M1/M2 polarization of tumor-associated macrophages." (PMID 33155039, 2020). "Loss of host-derived MIF resulted in a decrease in intrasplenic and intratumoral Tregs following tumor inoculation and this corresponded with an increase in splenic CD4+ and CD8+ T cells and a decrease in tumor outgrowth." (PMID 33324425, 2020). "One such study found that loss of tumor-derived MIF significantly enhances DC tumor accumulation, effector functions and, anti-tumor immunity." (PMID 33324425, 2020). "Collectively, these studies clearly point to a centrally important role for MIF in driving tumor-associated MDSC phenotypes." (PMID 33324425, 2020). "MIF expression has been previously associated with poor prognosis and early tumor recurrence in GBM14–16." (PMID 30814573, 2019). "Actually, in vivo experiments on wild-type and MIF−/− mice, in which MIF deficient tumor cells were implanted, showed a decreased angiogenesis in the MIF−/− mice but not in the wild-type individuals." (PMID 31013837, 2019). "Xenograft tissue-derived supernatants were blotted on a human cytokine array and macrophage migration inhibitory factor (MIF) was found downregulated in CI-deficient tumor-derived secretome." (PMID 31835761, 2019). "These increased pro-tumor properties were associated with a substantially increased expression in Src/CD155/MIF expression and stemness markers such as Notch1 and β-catenin." (PMID 31036057, 2019). "In animal models of cancer, it was demonstrated that MIF had the potential to promote tumor growth and tumor-associated angiogenesis and that anti-MIF antibodies suppressed angiogenesis in these models." (PMID 31866994, 2019). "MIF promotes alternative macrophage differentiation that lead to formation of tumor-associated macrophages (TAMs)." (PMID 30981278, 2019). "Several studies proposed that the MIF/CD74 signaling pathway is an important regulator in pathological tumor-associated angiogenesis and showed that MIF expression levels correlated with tumor angiogenesis." (PMID 31866994, 2019). "These phenomena led to a higher tumor immunosuppression by TAMs in MIF-deficient mice than in wild-type individuals." (PMID 31013837, 2019). "MIF was proposed as the link that connects the inflammatory response to tumor-associated angiogenesis." (PMID 31866994, 2019). "Collectively, these results suggest that loss of MIF expression in the primary tumor results in an enhanced early anti-tumor T cell response, leading to decreased tumor outgrowth." (PMID 29864117, 2018). "We have demonstrated that, in the 4T1 model, loss of MIF expression leads to a robust increase in activated DCs intratumorally by day 8 of tumor growth." (PMID 29864117, 2018). "As in the MMTV-PyMT model, and consistent with our previous work, loss of MIF expression in the primary tumor reduced tumor growth in the 4T1 model." (PMID 29864117, 2018). "Using the MMTV-PyMT model, we observed that MIF-deficiency lead to a reduction in overall tumor burden as well as a delay in tumor occurrence, further supporting the role of MIF in promoting tumor growth." (PMID 29864117, 2018).